PDZK1P1 (PDZ domain containing 1 pseudogene 1)
Synonyms: OTTHUMT00000038524; OTTHUMG00000074107; formerly PDZK1P2
Gene: Transcribed unprocessed pseudogene on chromosome 1 (147,994,301 to 148,009,592, reverse strand). Ensembl gene ENSG00000215859.
Diseases named in the same sentence as PDZK1P1 in open-access papers:
PDZK1P1 is named in the same sentence as 1 disease in open-access papers, as found by Europe PMC text mining. Sharing a sentence is not in itself a finding about the gene and the disease.
PDZK1P1 shares sentences with these, for which no sentence is quoted: congenital hypothyroidism (1 paper).